SFRP1 (secreted frizzled related protein 1)
Diseases named in the same sentence as SFRP1 in open-access papers (continued):
Sharing a sentence is not in itself a finding about the gene and the disease.
benign prostatic hyperplasia (1 paper, 2015). A non-cancerous nodular enlargement of the prostate gland. "Immunohistochemical staining of SFRP1 and β-catenin proteins in human PCa versus benign prostatic hyperplasia." (PMID 25719802, 2015). "In this study, a total of 61 patients with PCa and 10 patients with benign prostatic hyperplasia were included, and we showed that the expression of SFRP1 and β-catenin was correlated with the Gleason score, survival rate and response for endocrine therapy of PCa." (PMID 25719802, 2015). "We observed that the SFRP1 expression was reduced in PCa samples compared with that in benign prostatic hyperplasia samples from 80% to 59% and its expression was inversely correlated with β-catenin expression, consistent with their expression patterns in other tumor samples." (PMID 25719802, 2015). "According to the rating criteria, 8 (80%) of the 10 benign prostatic hyperplasia samples were classified as positive for SFRP1 expression and 2 (20%) were classified as negative, whereas in tumor samples, SFRP1 expression significantly decreased with 36 (59%) positive and 25 (41%) negative." (PMID 25719802, 2015).
brain tumor (1 paper, 2020). "The results of the MS‐HRM analysis of all analyzed genes (SFRP1, SFRP2, RUNX3, CBLN4, INA, MGMT, and RASSF1A) showed that their promoter sequence methylation level is significantly higher (P < 0.0001) in DNA samples from brain tumor patients than in the non‐neoplastic brain sample." (PMID 32783304, 2020).
chronic hepatitis (1 paper, 2018). An active inflammatory process affecting the liver for more than six months. "Furthermore, they also demonstrated that sFRP1 promoter methylation decreased significantly compared to the HCC patients (48.2%), than in patients with cirrhotic liver (21.4%) and chronic hepatitis (14.3%)." (PMID 30513115, 2018).
chronic kidney disease (1 paper, 2026). Impairment of the renal function secondary to chronic kidney damage persisting for three or more months. "This study aimed to examine the association between serum Secreted Frizzled-Related Protein 1 (SFRP1) levels and the presence of coronary artery calcification (CAC) in patients with Stage 5D chronic kidney disease (CKD) undergoing maintenance hemodialysis (MHD)." (PMID 42187504, 2026).
chronic lymphocytic leukemia (1 paper, 2013). "Of note, the DNA hypermethylation in TSGs, such as DAPK1, ID4, SFRP1, TWIST2 and ZAP70, has been identified to play a role in the pathogenesis or prognosis of chronic lymphocytic leukemia (CLL)." (PMID 24373626, 2013).
cognitive decline (1 paper, 2025). "Glial cell-derived SFRP1 can localize to the synapses and cause synaptic dysfunction, resulting in cognitive decline." (PMID 41189817, 2025). "Glial cell-derived SFRP1 is localized to the synapses of the APP/PS1 mouse brain, leading to synaptic dysfunction and cognitive decline." (PMID 41189817, 2025).
cognitive deficits (1 paper, 2020). "Decreased SFRP-1 function lowers senile plaque accumulation, preventing LTP loss and cognitive deficits." (PMID 32850846, 2020).
colitis (1 paper, 2015). Inflammation of the colon. "Aberrant methylation of APC2 (adenomatousis polyposis coli 2), SFRP1 (secreted frizzled-related protein 1), and SFRP2 (secreted frizzled-related protein 2) is associated with the progression from colitis to neoplasia." (PMID 26101583, 2015).
cortical dysplasia (1 paper, 2023). "SFRP1, LRP6, FZD4 and CTNNBIP1 genes showed very similar percentage delta CT values in control tissue and NAAC and with a difference in these delta values in tissue with cortical dysplasia." (PMID 37749503, 2023).
corticotropinomas (1 paper, 2024). "In this work, we have shown the significant downregulation of RSPO2 (agonist) and SFRP1 (antagonist) in WNT signaling in USP8-mutant corticotropinomas, which supports our hypothesis on the role of USP8-mutation-altered WNT signaling regulation in these tumors." (PMID 39684597, 2024).
depression disorders (1 paper, 2023). "sFRP1 (secreted frizzled protein), which can inhibit both canonical and noncanonical Wnt pathways and is reportedly linked to neurogenesis processes and depression disorders, was markedly higher in the HSPP group." (PMID 37491227, 2023).
endometrioid carcinomas (1 paper, 2018). "In our series, hypermethylation of the Wnt antagonists (DKK1, DKK2, SFRP1, SFRP4, SFRP5, and WIF1) were observed with a significant prevalence in mucinous and endometrioid carcinomas." (PMID 29882921, 2018).
epilepsy (1 paper, 2023). A brain disorder characterized by episodes of abnormally increased neuronal discharge resulting in transient episodes of sensory or motor neurological dysfunction, or psychic dysfunction. "However, there are still relatively few relevant studies, and our results could help to target the cellular subpopulation of SFRP1 in epilepsy and refine the antagonistic role of SFRP1 in epilepsy." (PMID 36776884, 2023).
gastric intestinal adenocarcinoma (1 paper, 2021). "The expression of SFRP1/5 was lower in gastric intestinal adenocarcinoma of NOS." (PMID 34205081, 2021).
gastric tumors (1 paper, 2024). "SFRP1, a Wnt pathway antagonist, is regulated by promoter hypermethylation in colon and gastric tumors, and similar epigenetic regulation may occur in IBS-D, affecting inflammatory processes." (PMID 39273274, 2024).
hair loss (1 paper, 2026). "We investigated whether targeting Dickkopf 1 (DKK1) and Secreted frizzled-related protein 1 (SFRP1), two AR-regulated genes, offers a novel therapeutic strategy for hair loss." (PMID 41751951, 2026).
hip fracture (1 paper, 2019). Traumatic or pathological injury to the hip in which the continuity of either the femoral head, femoral neck, intertrochanteric or subtrochanteric regions is broken. "After adjusting for age, BMI, family history of hip fracture, physical activity, and glucocorticoid use, the serum level of sFRP‐1 was positively correlated with lumbar spine BMD (β = 0.040, p < 0.001) and hip BMD (β = 0.011, p = 0.001)." (PMID 31372588, 2019).
hyperplastic polyp (1 paper, 2015). A polyp found mainly in the stomach and colon. "Additionally, 50 % of hyperplastic polyps revealed hypermethylation for SFRP1 relative to normal mucosa (p = 0.030)." (PMID 26203307, 2015).
invasive carcinoma (1 paper, 2023). A carcinoma that is not confined to the epithelium, and has spread to the surrounding stroma. "Public dataset analyses have also confirmed that the decrease in SFRP1 expression among tumoral tissue compared to non-tumoral tissue could be mediated by its promoter, hypermethylation, in luminal and HER2 invasive carcinomas." (PMID 37190179, 2023).
ischemia (1 paper, 2016). A hypoperfusion of the BLOOD through an organ or tissue caused by a PATHOLOGIC CONSTRICTION or obstruction of its BLOOD VESSELS, or an absence of BLOOD CIRCULATION. "The present study was designed to investigate the possible protective actions of Sfrp1 on cardiac muscle cells using an in vitro model of ischemia/reperfusion, and to evaluate the possible involvement of the Wnt signaling pathway." (PMID 27048460, 2016).
laryngeal carcinoma (1 paper, 2024). Carcinoma that arises from the laryngeal epithelium. "The direct regulation of EZH2 on SFRP1 in osteoarthritis and laryngeal carcinoma has been reported before." (PMID 38566211, 2024).
leukoplakia (1 paper, 2024). A white patch or plaque on a mucous membrane that cannot be characterized clinically or pathologically as any other disease. "During the progression from leukoplakia to HNSCC, we found several prognostic cell subgroups, such as AURKB + epithelial cells, SFRP1 + fibroblasts, SLC7A8 + macrophages, FCER1A + CD1C + dendritic cells, and TRGC2 + NK/T cells." (PMID 38582791, 2024).
liver disease (1 paper, 2008). "Of interest was the progressive accumulation of the FZD activating events (WNT3/4/5A and FZD3/6/7 upregulations and sFRP1/5 repression) with severity of the liver disease and the tumour stage." (PMID 18577996, 2008). "We have identified eight potential FZD activating events, each occurring in a significant proportion of HCCs (⩾20%) – that is, upregulation of FZD3/6/7 and WNT3/4/5A, and repression of sFRP1/sFRP5 – which accumulate with severity of the liver disease and tumour stage." (PMID 18577996, 2008).
metastatic melanoma (1 paper, 2026). A melanoma that has spread from its primary site to another anatomic site. "Results: sFRP1 expression was consistently elevated in metastatic melanoma cell lines, xenograft models, and TCGA datasets, and high sFRP1 expression was associated with poor overall survival." (PMID 42279305, 2026). "Secreted frizzled-related protein 1 (sFRP1) exhibits context-dependent roles in cancer; however, its function in metastatic melanoma remains poorly defined." (PMID 42279305, 2026).
microcephaly (1 paper, 2018). A congenital or acquired developmental disorder in which the circumference of the head is smaller than normal for the person's age and sex. "Knockout of Wnt7a in mice causes microcephaly due to reduced NP population and neurogenesis, and Sfrp1 has an opposing effect compared to Wnt7a." (PMID 30065628, 2018).
mucinous carcinomas (1 paper, 2018). "There are six genes (MAL, MYOD1, OSMR, SEPTIN9, SFRP1, and SFRP4) for which hypermethylation is observed almost exclusively or preferentially in mucinous carcinomas." (PMID 29882921, 2018).
myelodysplastic syndrome (1 paper, 2021). A clonal hematopoietic disorder characterized by dysplasia and ineffective hematopoiesis in one or more of the hematopoietic cell lines. "In a myelodysplastic syndrome (MDS) cell line, SFRP1 is transcriptionally inactivated due to epigenetic modification, allowing increased WNT ligand binding to FZD3." (PMID 34604862, 2021).
nasal polyp (1 paper, 2024). "Interestingly, within the CRS subtypes, there was very high expression of SFRP1 and SFRP2 in CRSsNP, which suggests that fibroblasts may regulate EpC Wnt signaling in CRS and highlights the possibility that unopposed EpC Wnt signaling may contribute to nasal polyp formation." (PMID 38444858, 2024).
oral cancer (1 paper, 2022). "However, our current understanding of the underlying mechanisms of SFRP1 is still very limited and its molecular function in oral cancer cells is yet to be revealed." (PMID 35892344, 2022). "Relevant studies of OSCC that evaluated the expression level of SFRP1 showed that it was dramatically down-regulated in tumor samples compared to control ones (p < 0.001, n = 32 versus n = 329, 3.67 ± 2.10 versus 5.91 ± 1.57), which suggested a role for SFRP1 as a suppressor in oral cancer." (PMID 35892344, 2022).
oropharyngeal cancers (1 paper, 2015). Carcinoma, predominantly squamous cell, arising from the epithelial cells of the oropharynx. "In this regard, frequent hypermethylation of the negative regulators of this pathway (DKK-3, RUNX3, SFRP1, SFRP2, SFRP4, SFRP5, and WIF1) was observed in oral and oropharyngeal cancers." (PMID 25487617, 2015).
ovarian diseases (1 paper, 2023). "In addition, the deregulation of GSTM2 (DNA damage), SFRP1, and BMPR2 (involved in folliculogenesis) has been described in ovarian diseases." (PMID 36982971, 2023).
periampullary adenocarcinoma (1 paper, 2020). An adenocarcinoma that arises from the periampullary region. "Microarray analysis of SFRP1 in periampullary adenocarcinoma was obtained from the Gene Expression Omnibus GSE39409 dataset." (PMID 32764696, 2020).
prostate adenocarcinoma (1 paper, 2020). "We performed a co-expression analyses of SFRP1 and ERG in 494 prostate adenocarcinomas samples from the TCGA database; as expected, low positive correlation between SFRP1 and ERG expression was confirmed (Spearman and Pearson." (PMID 32694934, 2020).
pseudoexfoliation syndrome (1 paper, 2022). "It is reported that mouse eyes with SFRP1 expression could accelerate the aging process, resembling those found in pseudoexfoliation syndrome, a known age-related disease." (PMID 35568915, 2022).
pulmonary hypertensive (1 paper, 2011). "Expression of Wnt ligands (Wnt1, Wnt3a, and Wnt5a) and Wnt signaling upstream regulator genes (Frizzled1 and 2 receptors and sFRP-1) and intracellular effectors (Axin1 and GSK3β) were investigated in pulmonary hypertensive rat lungs, 3 and 5 weeks after MCT injury." (PMID 21533110, 2011).
rectal cancer (1 paper, 2016). A primary or metastatic malignant neoplasm that affects the rectum. "Ten of the 36 (EYA4, FOXI2, CNRIP1, SFRP1, ADHFE1, C2orf40, MAL, PHACTR3, SST, TMEFF2) were known as rectal cancer related genes with aberrant methylation." (PMID 27566576, 2016).
retinal dystrophies (1 paper, 2020). "Furthermore, differential SFRP1 expression among individuals may represent one of the many possible causes of the low genotype-phenotype correlation observed among individuals suffering of retinal dystrophies." (PMID 32198470, 2020).
schizophrenia (1 paper, 2022). A major psychotic disorder characterized by abnormalities in the perception or expression of reality. "Increases in SFRPs, as observed in FASD males, are known to reduce the number of synapses in different animal models, and genetic and developmental studies have identified SFRP1 as a susceptibility gene for schizophrenia and ASD." (PMID 35268026, 2022).
serous ovarian carcinomas (1 paper, 2019). "In high-grade serous ovarian carcinomas, SFRP1 protein loss has been described, and reduced expression was associated with promoter methylation, although the study did not investigate treatment effects." (PMID 31195594, 2019).
skin cutaneous melanoma (1 paper, 2018). "Interestingly, both the genes queried were highly ranked and showed opposite Cox coefficient signs, positive for JARID2 and negative for SFRP1, in several cancer types including skin cutaneous melanoma (SKCM) and breast invasive carcinoma (BRCA)." (PMID 30119689, 2018).
steatosis (1 paper, 2013). Increased lipid within the cytoplasm of cells. "Additionally, we observed increased steatosis in the livers of Sfrp1-/- mice." (PMID 24339864, 2013).
stomach adenocarcinoma (1 paper, 2020). "For the patients with gastric adenocarcinoma, low methylation of SFRP1 (high expression levels of SFRP1) was correlated with poor patient prognosis." (PMID 32764696, 2020).
thrombotic disease (1 paper, 2017). The formation of a blood clot in the lumen of a vessel or heart chamber; causes include coagulation disorders and vascular endothelial injury. "The thrombotic disease/inflammation progress-related protein PF4 and sFRP1, a member of the Wnt/fz signal-transduction pathway and related to myocardial repair, are significantly up-regulated in triple-vessel disease with/without left main stenosis." (PMID 28947991, 2017).
thyroid cancer (1 paper, 2021). "In one study of induced thyroid cancer in male mice, gonadectomy led to an upregulation of tumour-suppressor genes, Glipr1 and Sfrp1 suggesting that testosterone promotes thyroid cancer progression through the suppressed expression of these genes." (PMID 34572888, 2021).
type 2 diabetes (1 paper, 2024). "PAX5, functioning as a classical transcription factor, can regulate the expression of many genes, such as MYC, WAPL, and several type 2 diabetes-related genes, including SFRP1 and SYT12." (PMID 38926764, 2024).
valvular heart disease (1 paper, 2022). "In this study, we present baseline plasma concentrations of WNT-5a, sFRP-1, sFRP-5, and WIF-1 in patients with coronary and/or valvular heart disease." (PMID 36440011, 2022).
vascular dementia (1 paper, 2013). A degenerative vascular disorder affecting the brain. "In addition to brain-related function, SFRP1 acts as a potent angiogenic factor on vascularization after ischemic or hypoxia events induced by cerebral hypoperfusion, which could evidence the possible involvement of SFRP1 in the process of vascular dementia." (PMID 23936146, 2013).
tumor (252 papers, 2004 to 2026). "Analysis of a tissue microarray (TMA) cohort revealed that high SFRP1 expression was dramatically associated with poor prognosis and advanced tumor stages in CRC patients." (PMID 40225580, 2025). "FGFR2+ tumor cells were observed clustering near SFRP1+ cells, indicating a preferential association between the two." (PMID 40225580, 2025). "Specifically, in cluster 1, we found that the chemokine CCL19 produced by fibroblasts and markers of tumor-associated fibroblasts such as SFRP1, PI16, and ADH1B were significantly expressed." (PMID 40538442, 2025). "The transcript levels of canonical Wnt signaling targets in tumor tissues of Sfrp1-deficient mice were similar to those in WT mice in the early phase of tumor development but were markedly reduced in the late phase." (PMID 38625488, 2024). "There have been studies reporting methylation of SFRP1 gene as a diagnostic biomarker in plasma, feces and surgically removed tumor tissues of patients with CRC 43-45." (PMID 37859826, 2023). "SFRP1’s usefulness as a biomarker for chemotherapy response in BC is supported by associations with age and tumour grade." (PMID 35646102, 2022). "In conclusion, our data suggest that solely SFRP1 promoter hypermethylation is associated with a transcriptional silencing in HB tumor cell lines." (PMID 32189106, 2020). "SFRP1 has been classified as a tumor suppressor gene due to the loss of its expression in many human cancers." (PMID 32074995, 2020). "Here, we uncovered that the SFRP1 expression is significantly associated with the PRETEXT (PRE-Treatment EXTent of tumor) risk classification system." (PMID 32189106, 2020). "The SFRP1 methylation status was significantly associated with the gender, age at diagnosis, tumor type, differentiation, extrahepatic growth, resection margin and telomerase reverse transcriptase (TERT) mutations." (PMID 32189106, 2020). "SFRP1 has been classified as a tumor suppressor gene due to the loss of expression in various human cancers, which is mainly attributed by epigenetic inactivation via DNA methylation or transcriptional silencing by microRNAs." (PMID 32074995, 2020). "CGI methylation located in SFRP1 has also been shown to be indirectly associated with tumor progression and tumor stage as well as to directly lead to the occurrence of poor prognosis in RCC patients." (PMID 32832275, 2020). "In BC, downregulation of SFRP1 protein is associated with tumor progression and poor prognosis, which is in agreement with our results." (PMID 30647841, 2018). "Loss of SFRP1 likely contributes to tumor progression by altering the expression of a critical transcription factor in both the epithelium and the immune system." (PMID 28687085, 2017). "In this study, we investigate the context-specific associations of SFRP1–5 expression in over 8000 tumour and normal samples from 29 different cancers." (PMID 28218291, 2017). "Given their abilities to inhibit Wnt signalling, as well as the loss of SFRP1 in many cancers, this family is generally considered to be tumour suppressive." (PMID 28218291, 2017). "We show that only SFRP1 associates consistently with tumour suppressive functions, and that SFRP2 and SFRP4 typically associate with a poor prognosis concomitant with the expression of genes associated with epithelial-to-mesenchymal transition." (PMID 28218291, 2017). "It is a tumor suppressor gene encoding secreted frizzled-related protein 1 (SFRP1), a WnT antagonist controlling cell growth and neovascularization." (PMID 26198328, 2015). "Five genes (BNC1, COL14A1, CST6, PDLIM4, and SFRP1) demonstrated frequent tumor-specific promoter region methylation (>30%), associated with transcriptional silencing." (PMID 28326264, 2015). "Inactivation of SFRP1 is associated with constitutive Wnt signaling and an increased proliferation in tumor cells." (PMID 26170835, 2015).